PIEZO2 (piezo type mechanosensitive ion channel component 2)
Diseases named in the same sentence as PIEZO2 in open-access papers (continued):
Sharing a sentence is not in itself a finding about the gene and the disease.
cancer (23 papers, 2014 to 2026). A tumor composed of atypical neoplastic, often pleomorphic cells that invade other tissues. "The development of effective therapeutic strategies must be rooted in a comprehensive understanding of the complex mechanisms underlying the actions of PIEZO2 across different cancer types." (PMID 41327436, 2025). "The relationship between PIEZO2 and cancer stem cells and gene mutation in GC patients was analyzed, which saves time and work for clinical research in GC, and provides new therapeutic targets and research directions." (PMID 38216574, 2024). "The mechanosensing PIEZO2-initiated signaling pathway has associations with different characteristics of cancer invasion and metastasis." (PMID 38027033, 2023). "Recently, several studies have reported that the dysregulation of PIEZO2 is associated with cancer proliferation, angiogenesis and resistance to anticancer treatments." (PMID 31058608, 2019). "We additionally identified recurrent mutations in RYR2, FMN1, B3GNT9 and PIEZO2 in our discovery set of cancers, but the importance of these genes for bladder carcinogenesis remains uncertain." (PMID 24777035, 2014). "Critically, cancer-associated splicing dysregulation may disrupt the physiological balance of PIEZO2 isoforms, potentially through aberrant splicing factors or splice-site mutations altering isoform ratios." (PMID 41327436, 2025). "Thus, despite its potential role in multiple cancer types, more research is required to fully understand the roles played by Piezo2 in tumors and the underlying mechanisms through which this mechanosensitive ion influences cancer." (PMID 37762011, 2023). "Piezo2 expression levels were associated with the prognosis of patients with cancer." (PMID 35991548, 2022). "However, previous studies regarding the roles of PIEZO2 in cancer and the underlying mechanisms how PIEZO2 exerts its impact on cancer are still insufficient and need to be further elucidated." (PMID 31058608, 2019). "Herein, we explored PIEZO2 expression, prognosis and underlying mechanisms in cancer." (PMID 31058608, 2019). "However, PIEZO2 expression shows a high mutation ratio in cancer tissue from NSCLC patients." (PMID 30745454, 2019). "Despite significant advances, several key limitations impede the development of PIEZO2-targeted therapies for cancer.Substantial uncertainty persists regarding the specific roles of distinct PIEZO2 isoforms and splice variants." (PMID 41327436, 2025). "While several recent reviews have addressed general mechanotransduction or PIEZO1-related cancer signaling, a comprehensive synthesis dedicated specifically to PIEZO2—its context-dependent roles and translational implications—has been lacking." (PMID 41327436, 2025). "The roles of PIEZO2 in immune cell infiltration and radioresistance provide a framework for exploring its contributions to immune homeostasis and cancer progression." (PMID 41327436, 2025). "Given their proven therapeutic effects in other PIEZO2-related diseases, these fatty acids also show potential for use in cancer therapy, especially in relation to PIEZO2 modulation." (PMID 41327436, 2025). "The expression of the mechanosensory Piezo2 channel has already been described in different malignant tumors." (PMID 39001475, 2024). "A retrospective cohort of 125 patients whose breasts were resected for carcinoma was chosen to determine the relationship between Piezo2 and different clinical and histological variables." (PMID 39001475, 2024). "Last year, an extensive in silico analysis of Piezo2 expression, genetic relationships with immunological markers, and predictive functions in pan-cancer was performed." (PMID 37762011, 2023). "This study indicated that Piezo2 expression is cell- and tissue-dependent in different cancer types and is related to prognosis in several tumors." (PMID 37762011, 2023).
cancer (continued). "In the present study, we performed a comprehensive analysis to investigate the expression, genetic alteration, associations with immune indicators, and prognostic roles of Piezo2 across 33 cancers using the UCSC Xena, HPA, TIDE, GSEA, and cBioportal databases." (PMID 35991548, 2022). "In brief, our analysis suggested that Piezo2 expression had cell-type-dependent and tissue-dependent in different types of cancer." (PMID 35991548, 2022). "Although we have extensively explored the prognostic and immunological roles of Piezo2 expression in pan-cancer, there were some limitations to our analysis." (PMID 35991548, 2022). "Due to the inconsistency between the correlation of Piezo2 expression and various clinical stages in different cancers, we next examined the relationship between Piezo2 expression levels and the prognosis of patients with different cancers." (PMID 35991548, 2022). "These further confirmed that Piezo2 showed a tissue-dependent manner of regulating the immune environment and affecting prognosis in patients with cancer." (PMID 35991548, 2022). "Different types of cancer are characterized by an increased expression of both Piezo1 and Piezo2 whilst, in a few, they are downregulated, proof of their direct implication in these pathologies." (PMID 32635333, 2020). "The mRNA (E,F) and protein (G,H) expression of PIEZO1 and PIEZO2 in cancer tissue from NSCLC patients were significantly lower than that in the adjacent non-cancer tissues." (PMID 30745454, 2019). "Recently, some studies have also suggested that aberrant expression of PIEZO2 is involved in cancer onset and progression." (PMID 31058608, 2019). "PIEZO2, a mechanically activated ion channel, is believed to play important roles in the onset and progression of human cancers for a long time." (PMID 31058608, 2019). "The role of Piezo1 and Piezo2 channels in the development of inflammatory, cancer and/or neuropathic pain conditions remains to be explored in detail." (PMID 29497363, 2018). "These collective findings suggest that strategic PIEZO2 inhibition could simultaneously target multiple hallmarks of cancer." (PMID 41327436, 2025). "Although direct evidence that ultrasound activates PIEZO2 in cancer is limited, studies in other contexts have demonstrated that ultrasound-induced pressure waves can activate mechanosensitive ion channels and stimulate PIEZO expression, suggesting a plausible pathway for PIEZO2 activation." (PMID 41327436, 2025). "Targeting PIEZO2 activity holds promise for cancer treatment." (PMID 41327436, 2025). "In cancer, this splice-dependent functional plasticity likely contributes to the context-dependent roles of PIEZO2, where isoform composition may dictate pro- or antitumorigenic outcomes." (PMID 41327436, 2025). "Moreover, dietary factors and inflammatory signals can modulate PIEZO2 expression, suggesting that genetic or environmental regulation varies across cancers." (PMID 41327436, 2025). "Piezo2-dependent Ca2+ influx was shown to activate RhoA, a small GTPase protein that promotes the formation of actomyosin stress fibre (SFs) and focal adhesions (FAs), critical for mechanical force transmission, mechanotransduction, and cancer invasion." (PMID 40527011, 2025). "This apparently contradictory clinical/pathological finding remains to be further explored because, although Piezo2 overexpression was already noted in aggressive carcinomas, this is the first study including a cohort of more than 100 patients with complete morphological and clinical evaluation." (PMID 39001475, 2024). "In addition, the endothelial Piezo2 channel plays a role in peripheral pain mechanisms of painful peripheral neuropathy produced by cancer chemotherapy." (PMID 38054043, 2023). "PIEZO2 has been proposed to play a role in embryonic development, cell migration and cell differentiation, which are all important in carcinogenesis and cancer progression." (PMID 36077309, 2022).
cancer (continued). "Additional experiments were needed to prove the expression levels of Piezo2 in different cancers." (PMID 35991548, 2022). "It is, therefore, essential to explore the specific roles of Piezo2 in pan-cancer." (PMID 35991548, 2022). "Further studies are needed to fully elucidate PIEZO2 roles in cancer." (PMID 36077309, 2022). "Our study may further broaden the cancer landscape of Piezo2 and provide novel insights into cancer therapy." (PMID 35991548, 2022). "After the discovery of correlations between Piezo2 hypomethylation and T-cell dysfunction, we evaluated whether hypomethylation of Piezo2 could affect the prognosis of cancer patients." (PMID 35991548, 2022). "GO and KEGG analysis showed that Piezo2 was mainly enriched in cancer calcium signaling pathways." (PMID 35991548, 2022). "Roles of Piezo-type mechanosensitive ion channel component 2 (PIEZO2) in cancer remain largely unknown." (PMID 31058608, 2019). "Therefore, we postulated that methylation statuses of Piezo2 might drive the transcriptomic alterations of cancer cells." (PMID 35991548, 2022). "So, Piezo2 could be a novel target used for cancer treatment in the future." (PMID 35991548, 2022). "Furthermore, given that carcinogenesis is associated with significant changes in mechanical properties of the affected cells and tissues that contribute to the malignancy of the respective types of cancers, the expression of both Piezo1 and Piezo2 varies largely in different types of cancers." (PMID 35340591, 2022). "Furthermore, analysis of KEEG and GO in cancers suggested that Piezo2 could influence the activation of the immune response, antigen processing, and presentation pathways." (PMID 35991548, 2022). "We also explored whether Piezo2 expression affected the PFS of cancer patients." (PMID 35991548, 2022). "The Online database of cancer genes and GSE54129 have been used to analyze the clinical characteristics of PIEZO2 expression." (PMID 38216574, 2024). "The PT complex downregulated the gene expression of kinesin-1 light chain 2 (KLC2), mechanosensing PIEZO2, mitochondrial carrier homolog 2 (MTCH2), and ZDHHC14, which are known to enhance the invasion and migration of cancer cells." (PMID 38027033, 2023). "Thus, Piezo2 might exert cancer-promoting or cancer‐suppressing effects in various cancers." (PMID 35991548, 2022). "In addition, the iron channel protein PIEZO2 and its target protein NOTCH1/2 were upregulated (GEO database: GSE120194) 14 PIEZO is a mechanically sensitive channel protein that has recently been implicated in the development and progression of various cancers." (PMID 34976193, 2022). "In addition, based on the reactions of Piezo2 to ICB, we evaluated the predictive power of Piezo2 compared with several well-recognized cancer immune evasion biomarkers." (PMID 35991548, 2022). "The role of PIEZO2 in cancer has not been elucidated, although there is evidence of its involvement with angiogenesis." (PMID 36077309, 2022). "The relationship between the expression levels of Piezo2 and prognosis was not consistent in different cancers." (PMID 35991548, 2022). "Despite the absence of specific PIEZO2-targeted activators or inhibitors, its activity and expression can be indirectly modulated through interconnected pathways, suggesting novel strategies for cancer intervention." (PMID 41327436, 2025). "In the current experiment, we tested the hypothesis that Piezo2 could be the mechano-transducer in the BVs that mediates pain in painful DPN, since the murine model of cancer chemotherapy-induced painful peripheral neuropathy plays a role in vascular pain for Piezo2." (PMID 38054043, 2023). "The prognostic and immunotherapeutic roles of Piezo2 in pan-cancer have not been reported." (PMID 35991548, 2022). "Furthermore, the expression and prognostic role of PIEZO2 in human cancers, to date, have also not been fully determined." (PMID 31058608, 2019).
cancer (continued). "Moreover, the most recent study, focused on triple-negative breast cancer, found similar results to the Piezo1 study, as elevated PIEZO2 mRNA expression was correlated with worse prognosis and lung metastases, finding no significant relation in hormone-positive carcinomas." (PMID 39001475, 2024). "However, the involvement of Piezo2 in different types of cancer has not yet been widely described." (PMID 37762011, 2023). "However, the functional role of Piezo2 has not received much attention in cancers." (PMID 35991548, 2022). "PIEZO2’s role in non-TNBC, as well as in other types of cancer, is yet to be determined." (PMID 36077309, 2022).
peripheral neuropathy (3 papers, 2015 to 2024). A disorder affecting the peripheral nervous system. "Attenuation of endothelial function, with octoxynol-9 or peripheral administration of ODN antisense to Piezo2 mRNA, both attenuated mechanical hyperalgesia in this model of chemotherapy-induced painful peripheral neuropathy, without affecting baseline paw withdrawal threshold in control rats." (PMID 26497944, 2015).
genetic diseases (2 papers, 2019 to 2021). "Furthermore, mutations in human PIEZO1 and PIEZO2 genes have been linked to various genetic diseases due to alterations in channel properties." (PMID 30745454, 2019). "For variants found within genes that have recently been linked to a genetic disorder and for variants with uncertain significance, such as ones located within KAT6A and PIEZO2, further work was carried out to assess their pathogenicity." (PMID 34324503, 2021). "More importantly, various genetic diseases caused by alteration of channel properties are associated with mutations in human PIEZO1 and PIEZO2 genes." (PMID 30745454, 2019).
infection (2 papers, 2016 to 2023). The state of being infected such as from the introduction of a foreign agent such as serum, vaccine, antigenic substance or organism. "In contrast to the scrambled control shRNA (AAV-shScr) (Fig. 2dlower), there was a complete knockdown of Piezo2 expression after infection with AAV-Piezo2-sh-1 (Fig. 2dtop), which was confirmed immunohistochemically." (PMID 27184818, 2016).
myopathy (1 paper, 2025). A disease of the muscle in which the muscle fibers do not function properly. "Comparison of RNA sequencing data for 29 nonfailing and 31 ischemic cardiomyopathy hearts suggested increased PIEZO1 and PIEZO2 mRNA in myopathy." (PMID 40721314, 2025). "Therefore, although PIEZO2 may also protect against myopathy, it might be because of roles it has in other cell types of the heart." (PMID 40721314, 2025). "Upregulated PIEZO1 mRNA and PIEZO1 proteins were also suggested in a separate study of human dilated cardio-myopathy heart samples, with no change in PIEZO2 mRNA." (PMID 40721314, 2025).
PIEZO2 also shares sentences with these, for which no sentence is quoted: Arthritis (2 papers); cardiovascular disease (2); heart failure (2); lung carcinoma (2); neuromuscular disease (2); respiratory disease (2); Respiratory insufficiency (2); Sleep apnea (2); anemia (1); ankylosing spondylitis (1); ankylosis (1); anxiety depression (1); attention deficit-hyperactivity disorder (1); autism spectrum disorder (1); bipolar disorder (1); brain cancer (1); brain malformations (1); breast neoplasm (1); carcinoid (1); cocaine dependence (1); Cognitive impairment (1); dehydrated hereditary stomatocytosis (1); diabetic nephropathy (1); Dry skin (1); eating disorder (1); endometrial cancer (1); fibromyalgia (1); growth deficiency (1); Headache (1); hypertensive heart disease (1).
A further 42 diseases each share a sentence with PIEZO2 in 1 paper.